TNF (tumor necrosis factor)
Diseases named in the same sentence as TNF in open-access papers (continued):
Sharing a sentence is not in itself a finding about the gene and the disease.
COVID-19 (continued). "The consumption of omega-3 fatty acids has been shown to lower markers of inflammation in serum, such as C-reactive protein, interleukin-6 (IL-6), interleukin-1β (IL-1β), and tumor necrosis factor-α (TNF-α), and other inflammatory factors that have been implicated in the cytokine storm of COVID-19." (PMID 37515117, 2023). "In ECMO patients with COVID-19, the level of TNF-α is associated with disease severity and death." (PMID 37342247, 2023). "A clinical study of 1439 IBD patients from 47 countries showed that combination therapy (TNF antagonist and thiopurine) and thiopurine drugs may increase the risk of severe COVID-19." (PMID 37016327, 2023). "While immunosuppressants can reduce cytokine storms triggered by TNF, IL-1, IL-6, and interferon, which may mitigate serious organ damage in COVID-19 patients, they also increase the risk of infections due to a reduced autoimmune response." (PMID 37163438, 2023). "ARDS is the leading cause of death due to COVID-19, characterized by high levels of pro-inflammatory cytokines (IL-6, IL-17, IL-1β, and TNF-α) and immune cell hyperactivation, a state called “cytokine storm” that may lead to multiorgan failure." (PMID 37368708, 2023). "In addition, elevated levels of the proinflammatory cytokines IL-6 and TNF-α in COVID-19 patients cause damage to the lymphatic system, resulting in immunosuppression, which contributes to the progression of TB." (PMID 38162574, 2023). "Particularly, an increased susceptibility for Candida infections in critically ill COVID-19 patients was suggested by the observation of impaired immune response to those pathogens characterized by the abrogated release of IL-6, TNF, IL-1α, and IL-1β toward Candida albicans." (PMID 36675940, 2023). "Indeed, a large meta-analysis of cytokine measurements in ARDS patients of different causes revealed lower levels of inflammatory markers, such as IL-6 and TNF-α, in COVID-19-associated ARDS." (PMID 37283766, 2023). "Plasma gelsolin is particularly effective towards S1-induced IL-8 and TNF-α secretion, both cytokines with a potent ability to impair endothelial permeability that has been widely associated with poor clinical outcomes for patients with COVID-19." (PMID 36434734, 2022). "The comparative analysis of TNF-antagonist monotherapy, combination therapy (adjusted OR 4.01, 95% CI 1.65–9.78), and thiopurine monotherapy (adjusted OR 4.08, 95% CI 1.73–9.61) showed a significantly increased risk of severe COVID-19." (PMID 35448412, 2022). "GSDME was also shown to be cleaved in PBMCs of healthy donors after treatment with a combination of TNF-α and IFNγ, two cytokines linked to COVID-19 severity, further indicating a potential role of GSDME as a backup mechanism for cell death during SARS-CoV-2 infection." (PMID 35244141, 2022). "According to clinical studies, an abnormal concentration of various cytokines (such as TNF-α, IL-6, IL-8) and an excessive release of reactive oxygen species in COVID-19 could cause an overactive immune response in COVID-19." (PMID 36210820, 2022). "Independent associated factors of serum IL-6 and TNF-α levels in COVID-19 patients (n = 218)." (PMID 36419783, 2022). "This study aims to investigate whether TNF-α, IL-6, and vitamin D levels are associated with COVID-19 severity and mortality." (PMID 35215138, 2022). "Furthermore, clinical reports have associated COVID-19 severity with elevated blood cytokine levels of TNFα and IL-1β." (PMID 36136963, 2022). "Tumor necrosis factor-alpha (TNFα) expressed by various innate and adaptive immune cells is a multifunctional proinflammatory cytokine that is robustly expressed and associated with severe malaria, as it is with severe COVID-19." (PMID 36415655, 2022). "The benign course of COVID-19 in our patients may be linked to the very low number of chronic corticosteroids used and the possible protective effect of anti-TNF agents, which were the main class of biologics herein employed." (PMID 35891442, 2022).
COVID-19 (continued). "As a result, puerarin’s mechanism of action in the therapy of EHF/COVID-19 could be associated with the IL-1, TNFα, and VEGF signaling pathways." (PMID 35663983, 2022). "Among these cytokines, MCP-1 and TNF-α could be promising biomarkers for the identification of patients at risk for severe COVID-19, representing possible targets of intervention to limit COVID-19 severity." (PMID 35164139, 2022). "IL-6 and TNF-α may be the most critical factors causing CS; IL-6 and IL-10 levels can be used as a primary index for predicting COVID-19 outcomes." (PMID 36278166, 2022). "The role of the rs1800629 polymorphism in the TNF gene has been widely discussed due to many inflammatory diseases, but there are virtually no publications on its role in the susceptibility and/or severity of COVID-19." (PMID 35327350, 2022). "The aim of this study was to explore whether the TNFα.− 308A > G polymorphism affects the clinical state of COVID-19 patients." (PMID 37521833, 2022). "Similarly, TNF α levels in patients with COVID-19 were increased, and they were closely associated with increased disease severity." (PMID 36012146, 2022). "The US diet contains large amounts of n-6 fatty acids (including arachidonic acid, which is converted into leukotrienes, and thromboxanes) and increased cytokines, such as interleukin (IL)-1, IL-6, and tumor necrosis factor, which are risk factors for COVID-19." (PMID 35276992, 2022). "Nevertheless, other studies have associated TNF-mediated inflammation with chronic fatigue before, which is one of the most commonly reported symptoms in individuals who suffer from long-lasting COVID-19 symptoms." (PMID 36405747, 2022). "As COVID-19 is associated with hypercytokinaemia, cytokines, like IL-1, IL-6 and TNFα, may induce cell death." (PMID 36514048, 2022). "The mechanism behind the development of lymphopenia in COVID-19 is suggested to be multi-factorial: direct cell infection by the virus, indirect destruction by hyper-inflammation caused via IL-6 and TNF-α pathways, and lymphocytes recruitment to the inflammatory lung tissues." (PMID 36453635, 2022). "In addition, we also addressed the role of COVID-19 superinfection-associated cytokines such as TNF-α, IFN-γ and IL-4, which synergistically mediate impaired antibacterial effector function in myeloid immune cells." (PMID 35007290, 2022). "This is the first study that shows the association of inhibin B with TNF-α in COVID-19 patients." (PMID 36381078, 2022). "The high omega-6/omega-3 ratio is extremely proinflammatory, leading to increased expression of CRP, leukotrienes, and ultimately high levels of cytokines including IL-6 of TNF-α that could increase the susceptibility of COVID-19." (PMID 35685606, 2022). "Although hyperinflammatory response influences the severity of coronavirus disease 2019 (COVID-19), little has been reported about the utility of tumor necrosis factor (TNF)-related biomarkers in reflecting the prognosis." (PMID 36219652, 2022). "In a COVID-19 cohort, the depletion of several bacterial species (B. adolescentis, E. rectale and F. prausnitzii, known to play immunomodulatory roles in the human GI system) was linked to increased plasma concentrations of TNF-α, CXCL10, CCL2 and IL-10." (PMID 35956081, 2022). "COVID-19 may be responsible for the perpetuation of arrhythmias due to an increased catecholaminergic state caused by cytokines such as IL-6, IL-1, and tumor necrosis factor-alpha." (PMID 36614901, 2022). "In order to explore the factors in the host, with the strongest effect on the clinical progression of COVID-19, we studied the − 308A > G polymorphism of TNFα gene located at the promoter region, which has been ascribed to the polymorphisms within the regulatory regions." (PMID 37521833, 2022). "In addition to IFNs, a number of pro-inflammatory cytokines, including members of the IL-1 family, IL-6, IL-8, and TNF have been implicated in COVID-19 pathogenesis and linked to severe disease." (PMID 36189236, 2022).
COVID-19 (continued). "Moreover, it is now known that patients with acute COVID-19 present increased blood levels of pro-inflammatory cytokines (e.g., IL-6, IL-8, TNFα) that drive neutrophil mobilization and are associated with poor prognosis in severe cases." (PMID 36466824, 2022). "Our recent studies have suggested that cannabis extracts may inhibit the TNFα/IFNγ-induced inflammatory cytokine expression implicated in COVID-19." (PMID 35277472, 2022). "Therefore, the current study aimed to investigate lncRNAs, particularly NEAT1 and TUG1, and their association with IL-6, CCL2, and TNF-α in COVID-19 patients with moderate and severe disease." (PMID 35982898, 2022). "For example, in RA, anti-TNFα reduces the production of additional cytokines such as IL-1 and IL-6; therefore, blocking TNFα in COVID-19 could reduce these potentially pathogenic cytokines." (PMID 36579506, 2022). "Moreover, a case-control study highlighted that TNFα inhibitors, adalimumab in particular, significantly decreased the risk of developing COVID-19 in patients with RA." (PMID 36289890, 2022). "Additionally, it has been reported that the SARS-CoV S protein can upregulate IL-6 and TNF-α expressions through the NF-κB signaling pathway, increasing the levels of inflammatory factors in COVID-19 patients, and causing serious lung damage." (PMID 36364151, 2022). "Anti-TNF-α drugs, such as Infliximab, act as a mild anti-inflammatory and have a well-demonstrated ability to reduce levels of the cytokines associated with poor COVID-19 prognosis." (PMID 36037223, 2022). "Post-acute sequelae of COVID-19, also called Long-COVID, is as HF potentially caused by incomplete resolution of inflammation and characterized by a long lasting elevation of IL-1β, IL-6 and TNF-α." (PMID 35548445, 2022). "Additionally, the pathogenesis of COVID-19 is associated with elevated cytokines such as IL-1β, IL-6, and TNF-α." (PMID 36160713, 2022). "Moreover, studies are still required to adequately evaluate IFITM3, FURIN, and TNF-α genetic variants’ role in COVID-19 susceptibility and outcomes." (PMID 35432458, 2022). "The investigations on the critically ill COVID-19 patients with ARDS and sepsis indicated a negligible statistically significant difference in the circulating levels of interleukins and TNF-α, suggesting that the COVID-19-associated ARDS occurs due to the heightened inflammatory cytokine levels." (PMID 35315705, 2022). "In the case of COVID-19, there are two main unknowns related to TNF inhibitors: the risk of immunosuppression in the SARS-CoV-2 infection and the possibility that these agents could facilitate virus entry into target cells." (PMID 35631442, 2022). "Therefore, we focused our systematic review on IFITM3, FURIN, ACE1, and TNF-α genetic variants and their association with COVID-19 susceptibility and prognosis to reduce unnecessary duplication." (PMID 35432458, 2022). "A detrimental role for cytokines, specifically IFNγ and TNF, had been previously associated with severe COVID-19 and experimentally identified as a risk factor for severe disease in SARS-CoV-2-infected KRT18-hACE2 mice by causing a form of inflammatory cell death termed PANoptosis." (PMID 35023830, 2022). "The cytokine cascade, including interleukins, chemokines, interferons, and TNF-α which causes extensive tissue damage, is correlated with the severity of the infection and associated with the progression of COVID-19 and complications, the important causes of death in COVID-19 patients." (PMID 35656183, 2022). "Sera biomarkers that indicate cardiac damage, inflammation and thrombosis such as troponin T and I, CRP, tumor necrosis factor (TNF), IL-1β and IL-6 have been found to be associated with increased mortality as well as being elevated in males with COVID-19 compared to females." (PMID 36292038, 2022).
COVID-19 (continued). "Although plasma levels of TNF-α may be submitted to a multifactorial regulatory process, the local TNF-α concentration involved in the pathogenesis of COVID-19 may be under a major control by the A allele of the TNFα.− 308 polymorphism." (PMID 37521833, 2022). "Data from the SECURE-IBD and COVID-19 Global Rheumatology Alliance registries demonstrated that anti-TNF therapies in patients with inflammatory bowel disease and rheumatic disease infected with COVID-19 were associated with lower hospital admission, ventilator use, and death." (PMID 34858665, 2021). "The COVID-19 cytokine profile of patients is closely associated with cytokine release, indicating macrophage activation, and an increase in the level of cytokines such as the TNFα, IL-6 and interferon-gamma (IFN-γ)." (PMID 33927728, 2021). "Higher circulating levels of soluble VCAM-1 and E-selectin have been reported in patients with COVID-19, and are associated with elevated levels of pro-inflammatory cytokines and chemokines such as tumor necrosis factor-α (TNF-α), indicating endothelial injury." (PMID 34835015, 2021). "Besides these various cytokines, chemokines, inflammatory transcription factors like NF-κB, and TNF-α play a pivotal part in inflammation associated with COVID-19 patients." (PMID 34833873, 2021). "Moreover, it seems that Sitagliptin has proven efficacy against acute respiratory distress syndrome (ARDS), the common causes of COVID-19-related death, because this drug inhibits IL-6, IL-1, and TNF in individuals with lung injury." (PMID 34015003, 2021). "The results of this cohort study suggest that, among patients with IMIDs, receipt of TNF inhibitor monotherapy may be associated with a lower risk of COVID-19–associated hospitalization or death compared with other immunomodulatory treatment regimens." (PMID 34661663, 2021). "Moreover, these herbs suppressed pro-inflammatory cytokines including IL-6 or TNF-α, which were both identified in the cytokine storm of acute respiratory distress syndrome, a major cause of COVID-19 death." (PMID 35401158, 2021). "TNF, IL-10, and IL-8 are associated with the severity of COVID-19." (PMID 34046036, 2021). "IL-1β and its downstream effectors IL-6 and TNF-α are linked to the exacerbation of COVID-19." (PMID 34150848, 2021). "Interestingly, anti-TNF agents seemed to play a protective role in COVID-19, reducing the risk of hospitalization and ICU, ventilation or death." (PMID 34335579, 2021). "Our data collectively support the potential efficacy of JAK inhibitors and anti-TNF therapies in inflammatory macrophage responses in COVID-19 due to cellular phenotype associations with select inflammatory tissue diseases already proven to respond to these medications." (PMID 33879239, 2021). "Strikingly, current studies demonstrate an impaired type I IFN response associated with severe and critical COVID-19 patients, which inversely correlates with an excessive NF-κB–driven inflammatory response associated with increased TNFα and other inflammatory cytokines." (PMID 34108245, 2021). "Strikingly, combined stimulation of anti-spike IgG immune complexes and the toll-like receptor 3 agonist, polyinosinic:polycytidylic acid (poly(I:C)) increased the production of COVID-19-associated pro-inflammatory cytokines IL-1β, IL-6, and TNF compared to IgG or poly(I:C) alone." (PMID 33979301, 2021). "In separate work Pillai and colleagues have documented that germinal centers are lost in the lymph nodes and spleens of patients with acute COVID-19 and that aberrant TNF alpha production may underlie this anatomic destruction." (PMID 33969248, 2021). "Variants in cytokine genes such as IL1B, IL1R1, IL1RN, IL6, IL17A, FCGR2A, and TNF could be related to disease susceptibility and cytokine storm, and/or COVID-19 complications (e.g., venous thrombosis)." (PMID 33868239, 2021). "In addition, increased levels of cytokines (e.g., IL-6, IL-10, and TNF-α) have been associated with severe COVID-19." (PMID 34484133, 2021).
COVID-19 (continued). "In COVID-19, the loss of cytokine production (IL-2, IFNγ or TNFα) and antiviral activity (CD107a and Granzyme B) in both CD4+ and CD8+ T cells may be an important contributing factor to disease severity." (PMID 33575657, 2021). "Despite this pathogenic rationale, evidence of TNF blockade in COVID-19 is limited." (PMID 33669218, 2021). "Additionally, a potential caveat to using HbA as a countermeasure for COVID-19-induced hypoxia is that hemoglobin has been reported to cause stimulation of IL-6, IL-8, and tumor necrosis factor-α from leukocytes in whole blood." (PMID 34445747, 2021). "Indeed, therapies with anti-TNF were associated with better outcomes of COVID-19 in IBD patients who contracted SARS-CoV-2 infection and active phases of IBD are associated with a more severe course of COVID-19." (PMID 34362053, 2021). "In COVID-19, adiposity is associated with a preponderance of pro-inflammatory cells in hypertrophic adipocytes, that contribute to increases in serum cytokines, such as IL-6, TNF-alpha and CRP." (PMID 34383798, 2021). "These low IFN levels were associated with a persistent viral load in the blood and an exacerbated inflammatory response (overproduction and release of tumor necrosis factor-α [TNF-α] and IL-6), which may be a hallmark of severe COVID-19." (PMID 34593760, 2021). "TNF-α signaling via NF-kB is a target as it is associated with the inflammation-triggered CVDs, cancer cell migration and invasion, the pathogenesis of CKDs, and severity of COVID-19." (PMID 34067609, 2021). "Lee and coworkers reported that severe COVID-19 was associated with TNF-α and IL-1β signatures." (PMID 34319784, 2021). "We found that among IBD patients infected by COVID-19, anti-TNF agents were associated with lower incidences of hospitalization (OR 0.46, 95% CI 0.39-0.54, P<0.01), ICU (OR 0.37, 95% CI 0.25-0.54, P<0.01), ventilation (OR 0.30, 95% CI 0.19-0.48, P<0.01), and death (OR 0.21, 95%CI 0.11-0.38, P<0.01)." (PMID 34335579, 2021). "Data from the SECURE-IBD registry suggest that while the use of corticosteroids and thiopurines did increase the risk of severe COVID-19, the use of biologics, especially anti-TNF agents, may be protective." (PMID 34755037, 2021). "This cohort study found that TNF inhibitor monotherapy was associated with a lower risk of COVID-19–associated hospitalization or death among patients with IMIDs compared with other commonly used treatment regimens, including methotrexate, azathioprine/6-mercaptopurine, and Jak inhibitors." (PMID 34661663, 2021). "This cohort study uses data from 3 international registries to examine the association between the receipt of tumor necrosis factor monotherapy and the risk of COVID-19–associated hospitalization or death among adult patients with immune-mediated inflammatory diseases." (PMID 34661663, 2021). "Serum cytokine levels that are elevated in patients with COVID-19-associated cytokine storm include IL-1β, IL-6, interferon γ-induced protein-10 (IP-10), TNF-α, interferon-γ (IFN-γ), macrophage inflammatory protein (MIP) -1α and -1β, and vascular endothelial growth factor (VEGF)." (PMID 33807915, 2021). "TNF-alpha-induced endothelial cell apoptosis is also associated with endothelial injury, vascular permeability, and systemic capillary leak syndrome, all of which contribute to the progression of COVID-19." (PMID 34683480, 2021). "Furthermore, several studies reported increased IL-6 serum levels to be a hallmark of COVID-19, but also TNF and IL-8." (PMID 33441124, 2021). "Soluble TNF-R1 and sTNF-R2 act as decoy receptors for TNF-α; as such, patients with COVID-19 might be less capable of balancing pathogenic TNF-α activities than individuals with pandemic influenza A(H1N1)." (PMID 33995342, 2021).